CXCR4 (C-X-C motif chemokine receptor 4)
Diseases named in the same sentence as CXCR4 in open-access papers (continued):
Sharing a sentence is not in itself a finding about the gene and the disease.
tumor (continued). "Nonetheless, these results are supported by the cellular localization of CXCR4, differing according to cell type, tumor histology, and tumor stage." (PMID 38893721, 2024). "This notion was supported by the evidence that tumor-infiltrating myeloid precursors can upregulate CXCR4, a major homing receptor for the chemokine SDF-1, to recruit and retain them in tumor tissues." (PMID 39126041, 2024). "Overexpression of the Runt-related transcription factor 2 (RUNX2) has been reported in several cancer types, and the C-X-C motif chemokine receptor 4 (CXCR4) has an important role in tumour progression." (PMID 38474372, 2024). "Utilizing tumor-specific promoters such as CXCR4-promoter allows for tumor-specific transgene expression, driving high expression of therapeutic genes like GM-CSF and B7-1, thereby enhancing immune cell activation and infiltration into tumors." (PMID 38731910, 2024). "Anti-BCMA CAR-NK cells with CXCR4 mRNA electroporation reduced significantly multiple myeloma (MM) tumor burden and extended the survival of the tumor-bearing mice." (PMID 39633491, 2024). "We developed an 18F-labeled CXCR4-targeting tracer with suitable characteristics, such as high in vivo stability and rapid clearance of activity, leading to a favorable tumor-to-background ratio." (PMID 39431004, 2024). "The CXCL12/CXCR4 axis has been reported to be a key signalling axis for tumour growth and metastasis through the activation of multiple pathways, such as the p38, ERK1/2 and SAPK/JNK pathways." (PMID 38766687, 2024). "For instance, tumor-mediated suppression of BM stromal cells is reported to suppress SDF-1α levels in this compartment leading to poor infiltration of CXCR4+ lymphocytes." (PMID 38182818, 2024). "In HCC cells and nude mice, circ-0044539 downregulation or miR-29a-3p upregulation was associated with small tumor size, PI3K-AKT-mTOR pathway inactivation, and downregulation of the key LNM factors (HIF-1α and CXCR4)." (PMID 39191749, 2024). "The ICP-MS experimental result confirms the high tumor-targeting capability of anti-CXCR4-NaGdF4 NDs in tumor." (PMID 38982161, 2024). "On the other hand, CXCR4 blockade promoted T cell infiltration into the tumor, increased T cell anti-tumor activity, and improved immunotherapy treatments." (PMID 39596815, 2024). "CXCR4 antagonists are considered to have an important function in chemotherapy due to the interference between tumor and stromal cells." (PMID 38791414, 2024). "Chemokine receptor 4 (CXCR4) is overexpressed in the tumor microenvironment of more than 20 malignancies, including HNSCC." (PMID 39001265, 2024). "CXCL12-rich CAFs can impede CXCR4-expressing T cells from accessing tumor cells, hindering T cell infiltration." (PMID 39545420, 2024). "In contrast, for hematologic malignancies affecting the bone marrow, upregulation of CXCR4 expression is beneficial for improving homing to tumor cells." (PMID 38443448, 2024). "Selective inhibitors targeting CXCL12/CXCR4, such as plerixafor and BL-8040, have been investigated for their anti-tumor activities, showing variable effects in various cancers." (PMID 38898023, 2024). "CXCR4 overexpression can only be observed when the tumor relapses, indicating that E2A-PBX1 works together with other synergistic factors to regulate the expression of CXCR4 and enhance the drug resistance of tumor cells." (PMID 39129784, 2024). "The presence of CXCR4 has been observed to enhance the infiltration of CAR-T cells, thereby enabling CXCR4 CAR-T cells to more abundantly infiltrate tumor sites." (PMID 38920657, 2024). "For instance, blocking CXCR4 has been shown to reduce the recruitment of MDSCs and regulatory T cells to the tumor site, as these are known to suppress cytotoxic T lymphocytes and hinder effective anti-tumor immune responses." (PMID 39195225, 2024).
tumor (continued). "They found that the CXCL12 and CCL21 ligands and their corresponding receptors, CXCR4 and CCR7, were highly and significantly expressed in tumor cells with lymph node metastases associated with shorter survival in this cohort." (PMID 39001456, 2024). "Polymeric NPs containing CXCR4 DNA were used to upregulate CXCR4 in human adipose-derived stem cells to target tumor hypoxia." (PMID 39114657, 2024). "The impact of cancer cells is related to the interactions between tumour cell receptors (e.g., CXCR4 and RANKL) and the stromal cells of the bone marrow and bone matrix." (PMID 40757720, 2024). "Dysregulation of CXCL12 secretion by tumor cells and expression of CXCR4 by immunosuppressive cells induces the creation of an inhibitory TME by fostering the infiltration of the mentioned regulatory and cancer-associated cells." (PMID 39070795, 2024). "In vivo studies have demonstrated the involvement of several molecules in VCO tumor growth such as Bradikinin-2 receptor, chemoatractant system SDF1/CXCR4, Wnt7, the mutated receptor of EGFR (EGFRvIII) and ephrin-B2." (PMID 38255995, 2024). "The as-prepared anti-CXCR4-NaGdF4 NDs exhibits high longitudinal relaxivity (r1) value (21.87 mM−1S−1), reasonable biocompatibility and good tumor accumulation ability." (PMID 38982161, 2024). "CXCR4 is expressed on the macrophage surface, and it is involved in their tumor recruitment as well as in CAF interactions, desmoplasia, and T cell infiltration through the binding of its ligand, CXCL12." (PMID 38730724, 2024). "Recent advances in immunotherapy have highlighted the potential of targeting the SDF-1/CXCR4 pathway to enhance anti-tumor immunity." (PMID 39195225, 2024). "Based on our findings we conclude that co-modification of BCMA CAR-NK cells with CXCR4 exceeds functionalities related to improved trafficking and retention within tumor sites." (PMID 38979422, 2024). "Studies on osteosarcoma have shown that downregulation of YY1 negatively regulates the VEGF/CXCR4 axis pathway, thereby inhibiting angiogenesis and tumor cell migration by reducing the transcription and activity of MMPs." (PMID 38339244, 2024). "The expression level of CXCR4 in NEC patients with different tumor origins was significantly different (P=0.013)." (PMID 38524630, 2024). "Differential expression of CXCR4 was found between tumor and adjacent tissues and between NET G3 and NEC." (PMID 38524630, 2024). "The independent association of TRB, reflecting chemokine receptor density on the tumor cell surface, with a deteriorating outcome highlights the added value of molecular imaging targeting CXCR4 expression." (PMID 38896128, 2024). "A study comparing primary tumors derived from MDA-MB-231 xenograft mice to MDA-MB-231 parental cells grown in a cell culture showed that, with exogenous CXCL12, the primary tumor cells expressed more CXCR4 and activated PI3K/AKT signaling." (PMID 39766093, 2024). "Preclinical research across various cancers demonstrated that CXCR4+ monocytes recruited by tumor cells promote tumor angiogenesis." (PMID 38675738, 2024). "Exosomes from CRC increase the metastatic tumor distribution in the liver by recruiting C-X-C chemokine receptor type 4 (CXCR4)-expressing stromal cells to develop a pre-metastatic microenvironment." (PMID 38495881, 2024). "The CXCL12/CXCR4 pathway is believed to not only modulate the biological behaviors of tumor cells but also orchestrate the metastatic dissemination of CXCR4-positive tumor cells toward organs or tissues that express CXCL12." (PMID 39281319, 2024). "T cells are retained in the tumors by downregulation of CXCR4 upon encounter of intratumoral antigens, which ultimately promotes antitumor immunity and tumor control." (PMID 38786066, 2024). "This strategy also can target and eliminate CXCR4 myeloma cells, and fundamentally block the migration and extramedullary infiltration of tumor cells." (PMID 38244066, 2024).
tumor (continued). "Our strategy provides the advantages of avoiding CXCR4-related adverse effects and directly targeting tumor cells, thus having the potential to harmonize the anti-tumor effect of ICBs." (PMID 38898023, 2024). "For example, CXCR4 is overexpressed in many tumor types, including breast, lung ovarian, prostate, colon, melanoma and neuroblastoma." (PMID 39035006, 2024). "Certain chemokines, such as CXCL12 and its receptor CXCR4, promote tumor cell migration and invasion, facilitating metastasis to distant organs." (PMID 39001498, 2024). "The development of [68Ga]Ga-TD-01 marks a promising advancement in GBM PET imaging, providing high specificity for detecting CXCR4 expression in tumor tissues." (PMID 39162901, 2024). "The results of several studies have found that the CXCL12/CXCR4 axis is partly responsible for tumour progression, angiogenesis, metastasis, and survival." (PMID 38539419, 2024). "Since then, the link between CXCR4 and tumoral disease has been reviewed and, for instance, the implication of CXCR4 in more than 23 cancers is well known." (PMID 38791878, 2024). "IHC staining for CXCR4 in the brains of GBM-bearing mice confirm the presence of CXCR4 receptors on the cell membrane within tumor tissue." (PMID 39162901, 2024). "Last, a fraction of patients with [68 Ga]Ga-pentixafor-positive tumor burden were rendered potentially suitable for CXCR4-directed therapy." (PMID 38082196, 2024). "For example, the role of the CXCR4/SDF-1 axis in MSC homing to tumor sites has been well documented, but further research is needed to understand how this pathway interacts with other signaling mechanisms in the tumor microenvironment." (PMID 39576660, 2024). "The combination therapy downregulated immune response suppressors such as ApoE, CD69 and Cxcr4, which altered the transcriptome of CD11b+ cells to restore their anti-tumor function." (PMID 39239650, 2024). "CXCR4 targeting is a strategy to inhibit Tregs activity contributing to the CXCR4 function in the RCC tumour microenvironment." (PMID 38704478, 2024). "High expression of CXCR4 is closely related to increased tumor metastasis, and CXCR4 is involved in multiple processes related to metastasis, including chemotaxis, colonization and proliferation." (PMID 38321558, 2024). "This pattern was reversed at later time points, however, which can be attributed to the compensatory CXCR4 upregulation as well as the tumor infiltration by CXCR4-expressing immune cells." (PMID 38587644, 2024). "The flavonol fisetin exerted its anticancer activities in human non-small cell lung cancer cells A549 by reducing the expression of several tumor-promoting genes, including CXCR4." (PMID 39465008, 2024). "The CellChat results showed that the MIF/CXCR4 axis was the main crosstalk type between tumor cells and macrophages." (PMID 39464891, 2024). "The CXCL12/CXCR4 axis is also involved in tumor growth, tumor cell-microenvironment interactions, vasculogenesis and angiogenesis." (PMID 39035006, 2024). "The C-X-C chemokine receptor type 4/C-X-C motif chemokine 12 (CXCR4/CXCL12) interaction plays an important role in orchestrating tumor cells and CAFs." (PMID 38587644, 2024). "The E2F1-mediated inhibitory pathway of WNT5A expression and the CXCL12/CXC- chemokine receptor 4 (CXCR4) chemokine receptor signaling pathway facilitate the invasion of circulating tumor cells into the brain." (PMID 39328239, 2024). "Our data demonstrate that the primary tumor cells have a stronger CXCL12/CXCR4 signaling axis than the CTCs." (PMID 39766093, 2024). "CXCR4 is a crucial receptor involved in the interaction between tumor cells and their microenvironment." (PMID 39494324, 2024). "The tumor-permissive and immunosuppressive characteristics of CXCR4/CXCL12 axis have fueled interest in therapeutically targeting this signal pathway." (PMID 38587644, 2024).
tumor (continued). "C-X-C motif chemokine receptor 4 (CXCR4) plays a major role in tumor growth and the process of metastasis and is thus a highly attractive target in oncology." (PMID 39008062, 2024). "CD57+ NK cells tend to under-express the chemokine receptor CXCR4, affecting the homing of NK cells to the tumor primary site." (PMID 38410372, 2024). "CXCR4 also plays a major role in a pathophysiological environment such as promoting tumor growth, e.g. by support of cancer cell migration and the formation of distant metastasis." (PMID 39420354, 2024). "In this regard, analyses of tumor specimens have already demonstrated a substantial upregulation of this receptor subtype, which then triggered the use of the CXCR4-directed PET agent [68 Ga]Ga-pentixafor." (PMID 38082196, 2024). "CXCR4 is one of the key agents to monitor the crosstalk between the tumor cell and tumor microenvironment and promotes tumor progression." (PMID 39056802, 2024). "The addition of AMD to cisplatin had no additional anti-tumor effect in vitro, but improved the anti-tumor effect of cisplatin and reduced the number of CXCR4-positive blood vessels in cisplatin-resistant OSCC xenografts in vivo." (PMID 39001388, 2024). "The acetylation of KLF5 bolsters CXCR4 expression and interleukin‐11 secretion, fueling osteoclast differentiation and tumor cell plasticity in PCa bone metastasis." (PMID 38374872, 2024). "This study founds that CXCR4+ epithelial cells, identified as highly malignant disseminated tumor cells (DTCs), exhibited a propensity for lymph node metastasis." (PMID 39236316, 2024). "In the pre-metastatic niche, CXCL12 recruits circulating tumor cells with high CXCR4 and low Prrx1 expression from the bloodstream, ultimately promoting the metastatic colonization of distant organs." (PMID 38920657, 2024). "Nevertheless, HCC displays a more immunosuppressive TME due to Tregs, MDSCs, intrinsic tumor features (CXCR4, CCL5, arginase) and the contest in which it develops." (PMID 37142825, 2024). "Syndecan-2 expressed by tumor-associated stromal cells promotes the activation of TGF-β-mediated immunosuppressive genes, such as PD-L1 and C-X-C chemokine receptor type 4 (CXCR4)." (PMID 38946426, 2024). "Upon administration of a CXCR4-targeting drug to tumor cells, activating PDGFRβ as a compensatory mechanism enhanced cell proliferation." (PMID 39154307, 2024). "The spatial transcriptomic analysis reported herein revealed a compartmentalized expression pattern of CXCL12 in fibroblast-rich regions and CXCR4 in tumor regions dominated by KS signature cells, that is more pronounced in the PDX." (PMID 39386738, 2024). "The MIF/CXCR4 axis is the most common ligand–receptor interaction between macrophages and tumor cells." (PMID 39464891, 2024). "Considering the key role of CXCR4 in tumor immunosuppression, we investigated the immunomodulatory effects of P-BS-CM1 → P-CM2 on primary tumors." (PMID 38553476, 2024). "Increased CXCR4 expression in metastatic lesions correlates with tumor progression and with preferential metastatic sites of the primary tumor." (PMID 39035006, 2024). "The CXCL12/CXCR4 axis plays a pivotal role in tumor progression and metastasis, making it a promising therapeutic target in cancer." (PMID 39070795, 2024). "In contrast, an increasing prevalence of the pro-tumor E02-tip-CXCR4 manifested at the pan-cancer level." (PMID 39345334, 2024). "A semi-quantitative analysis of the CXCR4-positive tumor burden including maximum standardized uptake values (SUVmax) and target-to-background ratios (TBR) using blood pool was conducted." (PMID 38082196, 2024). "CXCR4 can regulate the evolution and progression of tumor cells through activating the chemokine signaling pathway." (PMID 39392257, 2024). "CXCL12 expression is elevated in multiple tumor types and engages receptors CXCR4 and CXCR7 to promote proliferation and survival of cancer cells and are detected in KS tumors." (PMID 39386738, 2024).
tumor (continued). "In another individual experiment, a consistent result was obtained for P-BS-CM1 → P-CM2 that exhibited no inhibitory effect on primary tumor, whereas AMD3100, a licensed CXCR4 antagonist, showed a dose-dependent anti-tumor activity." (PMID 38553476, 2024). "Here we asked to what degree does CXCR4 impact BCMA CAR-NK cell anti-tumor efficacy beyond BM homing and accumulation." (PMID 38979422, 2024). "There is a growing body of evidence suggesting the presence of CXCL12 and its specific receptor CXCR4 in various tumor cells, indicating their potential involvement in different stages of tumor progression." (PMID 38673838, 2024). "CXCR4 is known as a biomarker for tumor malignancy in multiple types of cancer, and the higher its expression, the higher the degree of tumor malignancy, making it more prone to metastasis, drug resistance, and so on 1,4." (PMID 39431004, 2024). "As with other types of neoplasms, the chemokine receptor CXCR4 is becoming increasingly relevant to researchers in the field of NENs." (PMID 38791878, 2024). "Using integrated scRNA-seq data, this study uncovers the compositional and functional heterogeneity of tumor endothelial cells, highlighting the angiogenic CXCR4+ tip cells and proinflammatory SELE+ veins, and their relationship with different treatments." (PMID 39345334, 2024). "The highly biocompatible BEVs targeted tumor cells in mice specifically with the AS1411 aptamer on their surfaces and lowered the expression of CXCR4, effectively lowering tumor proliferation." (PMID 38990415, 2024). "It has been reported that the binding of SDF-1 to the chemotaxis receptor CXCR4 promotes homing signal transduction, playing a pivotal role in tumor invasion, recurrence, and distant metastasis." (PMID 39195225, 2024). "The CXCR4 angiogenesis pathway differs from VEGF, making cisplatin–CXCR4 inhibitor combination therapy a novel approach for anti-tumor-vascular treatment." (PMID 39001388, 2024). "Overexpression of CXCR4 in cancer cells is known to lead to tumour growth, invasion, angiogenesis, metastasis, relapse, and therapeutic resistance to cancer." (PMID 38397018, 2024). "The CXCR4—CXCL12 axis regulates the transmission of diverse downstream signaling pathways crucial for tumor cell survival, proliferation, and migration, and PD-1/PD-L1 controls immune tolerance." (PMID 38727318, 2024). "Previous studies have confirmed that high expression of CXCR4 can promote tumor growth and metastasis." (PMID 38524630, 2024). "CXCR4 also contributes to immune suppression, supports tumor growth, and has the potential to chemoattract cancer cells to organs that produce its ligand, CXCL12, where cancer cells can establish secondary tumors." (PMID 38831458, 2024). "The C-X-C chemokine receptor 4 (CXCR4) plays an important role in tumour radioresistance and recurrence, and is considered as an interesting GBM target." (PMID 39008219, 2024). "Currently, there are many tumor environments in which CXCR4-positive cancer cells are highly likely to spread to tissues that express SDF1 (CXCL12), such as the bone marrow." (PMID 39154307, 2024). "At the same time, STEAP4+/ADGRF5+ fibroblasts and CXCR4+/SRGN+ fibroblasts alter tumor cells and immune cells in TME to promote lymphatic metastasis in PCa." (PMID 39470950, 2024). "Both in vitro experimental results and in vivo small animal experimental results with mouse-bearing MDA-MB-231 tumor indicate that anti-CXCR4-NaGdF4 NDs exhibit good tumor-targeted ability and biotherapeutic efficacy of tumor." (PMID 38982161, 2024). "The MIF/CXCR4 axis has been found to contribute to cell survival, drug resistance, and tumor metastasis in multiple types of tumors." (PMID 39464891, 2024). "PI3 kinase, Ras, and AKT are all downstream effectors of the CXCL12/CXCR4 axis, and activation of them promotes tumor cell growth, spread, and migration." (PMID 39065562, 2024).